ECE1 (endothelin converting enzyme 1)
Diseases named in the same sentence as ECE1 in open-access papers (continued):
Sharing a sentence is not in itself a finding about the gene and the disease.
hyperphosphatemia (2 papers, 2017 to 2020). Abnormally high level of phosphate in the blood. "In addition, hyperphosphatemia, which dramatically affects the behavior of vascular cells, increases ECE-1 activity in endothelial cells, which induces the synthesis of ET-1 and also senescence in endothelial cells." (PMID 32572011, 2020).
Obesity (2 papers, 2018 to 2024). Accumulation of substantial excess body fat. "Our expression analysis of ECE1 revealed its high expression in adipose tissue, especially in endothelial cells, and a positive association between obesity and VV risk has been demonstrated before." (PMID 38980841, 2024).
osteoporosis (2 papers, 2024 to 2025). A condition of reduced bone mass, with decreased cortical thickness and a decrease in the number and size of the trabeculae of cancellous bone (but normal chemical composition), resulting in increased fracture incidence. "However, the genetic variant rs213045 ECE1 may be related to the risk of osteoporosis." (PMID 39062013, 2024). "In our study, we analyzed the influence of the ECE1 rs213045 and rs213046 variants and the PPARG rs1801282 variant on the occurrence of osteopenia and osteoporosis in postmenopausal women." (PMID 39062013, 2024). "Due to the possible influence of the ECE1 gene on bone mineral density and the PPARG gene on the maintenance of bone mass, we selected several variants of these to assess their influence on the development of osteoporosis." (PMID 39062013, 2024). "Therefore, we analyzed the association of the ECE1 and PPARG variants with osteopenia and osteoporosis risk in the Polish population." (PMID 39062013, 2024). "In this study, we identified five key genes related to the circadian rhythm in osteoporosis (RAB5C, ECE1, FLT3, FCGR2A, and APPL1) using bioinformatics and machine learning approaches." (PMID 40642528, 2025).
pulmonary edema (2 papers, 2015 to 2024). Accumulation of fluid in the lung tissues causing disturbance of the gas exchange that may lead to respiratory failure. "The high altitude has decreased plasma levels of endothelin; it would be relevant that the raised levels of endothelin and greater expression of endothelin converting enzyme (ECE1) originated in lowland individuals who established high altitude pulmonary edema." (PMID 38187330, 2024).
breast carcinoma (1 paper, 2013). "For Mts-3 QTL candidate gene, Ece1, cumulative studies point to its role in breast cancer invasiveness and more frequent recurrence." (PMID 23967281, 2013).
chronic kidney disease (1 paper, 2020). Impairment of the renal function secondary to chronic kidney damage persisting for three or more months. "After injection of contrast media, endothelin significantly increased in healthy subjects and those with DN and chronic kidney disease (CKD); another study found endothelin converting enzyme-1 (ECE-1) also increased." (PMID 32788887, 2020).
colorectal cancer (1 paper, 2020). A primary or metastatic malignant neoplasm that affects the colon or rectum. "Additionally, similar decreases in invasiveness were observed in DLD‐1 and HT‐29 colorectal cancer cells after application of the ECE1 inhibitor SM19712 and siRNA silencing of ECE1c." (PMID 31788944, 2020).
colorectal tumor (1 paper, 2023). "In a model of colorectal tumor, we explored Tspan8 interacting molecules by mass spectrometry and found that compared to CD9, Tspan8 specifically recruits the endothelin converting enzyme ECE1 to tetraspanin-enriched microdomains and positively modulates its enzymatic activity." (PMID 37835445, 2023).
fibrosis (1 paper, 2024). the formation of excess fibrous connective tissue in an organ or tissue in a reparative or reactive process. "In line with this, we found an increased ACE, MMP2, and MMP7 mRNA expression, but also reduced APEH, ECE1, MBP, and NEP in samples with an advanced fibrosis grade." (PMID 39201455, 2024).
gingivitis (1 paper, 2018). A disorder involving inflammation of the gums; may affect surrounding and supporting structures of the teeth. "Of note, several gene products found to be increased in expression during gingivitis in our EC number analysis were found to be highly upregulated by P. nigrescens, including virulence factors endothelin-converting enzyme 1 and a gingipain." (PMID 29666288, 2018).
idiopathic pulmonary fibrosis (1 paper, 2024). Idiopathic pulmonary fibrosis (IPF) is a nonneoplastic pulmonary disease that is characterized by the formation of scar tissue within the lungs in the absence of any known cause. "Increased expression of ECE1 and its target endothelin-1 (Et-1) has previously been implicated in studies in pulmonary fibrosis in rat models and in human idiopathic pulmonary fibrosis and correlated with disease activity." (PMID 39363014, 2024).
lung carcinoma (1 paper, 2024). "High levels of endothelin-1 (ET-1), its cognate receptor ETAR and its activating enzyme, the endothelin-converting enzyme-1 (ECE-1), have been reported in several cancer types, including lung cancer." (PMID 39443981, 2024). "In fact, ET-1 is another b-catenin target whose expression increases in several cancers, including lung cancer, however, ET-1’s canonical mitogenic effects depend on its continuous activation by the enzyme ECE-1." (PMID 39443981, 2024).
lung hypoplasia (1 paper, 2017). "To exclude that the differences in expression patterns of the crucial prostacyclin – and endothelin receptors and the rate-limiting factor ECE-1 was solely an effect of lung hypoplasia (LH) or PH, we performed immunohistochemistry on lungs of patients with LH and PH with other cause than CDH." (PMID 29115963, 2017).
myocardial hypertrophy (1 paper, 2020). "The results of the present study showed that CPhGs significantly reduced ECE-1 demethylation, decreased ECE-1 mRNA and protein expression, and reduced plasma ET-1 levels in the myocardium of rats with pressure overload-induced cardiac hypertrophy after AAC." (PMID 32595726, 2020). "Our results showed that CPhGs ameliorated myocardial hypertrophy rats by AAC, which may be related to ECE-1 demethylation inhibition and PI3K/PKB/eNOS enhancement." (PMID 32595726, 2020). "In conclusion, CPhGs ameliorated myocardial hypertrophy rats by AAC, which may be related to ECE-1 demethylation inhibition and PI3K/PKB/eNOS enhancement." (PMID 32595726, 2020). "Overall, our study is the first to demonstrate the protective effect of CPhGs on pressure overload-induced cardiac hypertrophy in rats after AAC, which may be related to the role CPhGs play in effectively reducing the demethylation level of ECE-1 and enhancing the PI3K/PKB pathway." (PMID 32595726, 2020).
Osteopenia (1 paper, 2024). Osteopenia is a term to define bone density that is not normal but also not as low as osteoporosis. "The GG, GT, and TT genotypes of the ECE1 rs213045 variant were 57.1%, 37.4%, and 5.5% in the controls and 50.5%, 35.8%, and 13.8% in women with osteopenia (p = 0.037)." (PMID 39062013, 2024). "The results of a comparison of the haplotype frequencies of ECE1 gene variants showed that the haplotype containing two major GA alleles (rs213045, rs213046) reduces the risk of osteopenia in our population (p = 0.032)." (PMID 39062013, 2024). "We further observed that the haplotype containing two major GA alleles of ECE1 (rs213045, rs213046) could reduce the risk of osteopenia in our population." (PMID 39062013, 2024). "In summary, our study suggests that the ECE1 rs213045 variant may increase the risk of osteopenia." (PMID 39062013, 2024). "Additionally, our results suggest that the haplotype containing two major GA alleles of ECE1 (rs213045, rs213046) may reduce the risk of osteopenia, as seen in our population." (PMID 39062013, 2024). "Our results suggest that the ECE1 rs213045 variant may increase the risk of osteopenia." (PMID 39062013, 2024).
osteosarcoma (1 paper, 2023). A usually aggressive malignant bone-forming mesenchymal neoplasm, predominantly affecting adolescents and young adults. "However, the underlying mechanism of circRNA endothelin converting enzyme 1 (circECE1) in osteosarcoma (OS) development is still not understood." (PMID 37559140, 2023).
pulmonary fibrosis (1 paper, 2024). Chronic progressive interstitial lung disorder characterized by the replacement of the lung tissue by connective tissue, leading to progressive dyspnea, respiratory failure, or right heart failure. "In particular; due to the structural function in respiratory cilia, roles in vasoconstriction and existing implication in pulmonary fibrosis, DNAI1 and ECE1 respectively, are of great interest." (PMID 39363014, 2024).
Sepsis (1 paper, 2023). Sepsis is defined as life-threatening organ dysfunction caused by a dysregulated host response to infection. "Clearly, lethal sepsis from IAI-associated dissemination is not dependent on candidalysin (ece1) and does not discriminate against isolates that are sub-optimal for mucosal colonization." (PMID 37702509, 2023).
Ureteral obstruction (1 paper, 2025). Obstruction of the flow of urine through the ureter. "In order to do so, they measured ECE-1 and preproET-1 mRNA expression, and they performed histopathological analysis of the kidneys in ECE-1 knock-out mice, as well as in wild-type mice after unilateral ureteral obstruction." (PMID 41153763, 2025).
infection (23 papers, 2010 to 2026). The state of being infected such as from the introduction of a foreign agent such as serum, vaccine, antigenic substance or organism. "Another virulence factor of C. albicans is the ECE1 gene (endothelin converting enzyme 1 gene), which encodes a peptide toxin, candidalysin, which, by destabilizing the cell membrane of vaginal cells, facilitates infection and is responsible for the immunopathogenesis of fungal VVC." (PMID 38612606, 2024). "Disruption of the ECE1 locus or the region specifically encoding for candidalysin results in severe attenuation of pathogenicity in multiple infection models, including murine invasive and oral candidiasis, zebrafish swim bladder infection, and a variety of cell culture systems." (PMID 32106438, 2020). "ECE1 is one of the eight core filamentation genes in C. albicans induced in response to a wide range of different filamentation stimuli, suggesting an important and strictly morphology (hyphal)-associated role during infection." (PMID 32722029, 2020). "Other genes, such as EVA1A, which is involved in the regulation of autophagy and apoptosis, and ECE1 and Rab27b, which are associated with the growth, invasion, and metastasis of a variety of tumors, were also overexpressed in the context of vPdR-H30K-5U infection." (PMID 40006915, 2025). "Overall, these data indicate that the combination of hyphal growth and candidalysin production (demonstrated by the deletion of HGC1 and ECE1) is vital for driving infection in the tongue, with only a minimal contribution provided by ALS3 and SAP2." (PMID 41294335, 2026). "Since the expression of C. albicansECE1 (encoding candidalysin) is strongly induced during interactions with epithelial cells, we investigated the levels of ECE1 gene expression between species during infection of oral epithelial cells." (PMID 35073742, 2022). "The authors conclude by stating that the Ece1-III peptide is the first identified cytolytic peptide toxin secreted by a human fungal pathogen during infection, naming it Candidalysin." (PMID 27551525, 2016). "We reported in 2004 that inhibition of endothelin-converting enzyme-1 (ECE-1), which colocalizes with ET-1 in the placenta, controls PTD in a mouse model of infection-associated PTL." (PMID 20706662, 2010). "Additionally, C. albicans gene expression (ADH1, ECE1) was used to identify the infection loci sections." (PMID 40586608, 2025). "Similarly, deletion of ECE1 or candidalysin significantly reduces immunopathologic markers of infection (neutrophils, pro-inflammatory cytokines, alarmins) and tissue damage during experimental VVC." (PMID 32106438, 2020). "Thus, the apparent disparity between the candidalysin potency and fungal pathogenicity of these three Candida species can be explained by differences in hypha formation, hypha maintenance, and levels of ECE1 gene expression and candidalysin secretion during infection." (PMID 35073742, 2022). "Mouse infection experiments with C. albicans mutants lacking ECE1, or the candidalysin-encoding sequence only, showed that the candidalysin-dependent induction of IL-1β release transfers from the macrophage in vitro infection model to in vivo models of systemic candidiasis." (PMID 32722029, 2020). "Thus, the whole fungal morphological scenario and the correlations in gene expression in VVC appears to be typical of human infection, and incompatible with the popular assumption that SAP2 is a yeast, and SAP6, ECE1, and HWP1 are hyphae-associated in their expression." (PMID 31803172, 2019). "To study the influence of Candidalysin on inflammasome activation, we measured IL-1β secretion by LPS-primed primary hMDMs after infection with Wt C. albicans and mutants lacking the entire ECE1 gene (ece1Δ/Δ) or only the Candidalysin-encoding sequence (ece1Δ/Δ + ECE1Δ184–279)." (PMID 30323213, 2018).
infection (continued). "Nevertheless, these findings make us hypothesize whether pseudohyphal growth in C. auris is not one of the main pathogenic determinants upon infection, especially after hyphal-related proteins implied in pathogenesis such as candidalysin (ECE1) have not been detected in some works." (PMID 34890523, 2022). "We previously determined that ECE1 is downregulated by the human cytomegalovirus US2 protein and is modestly downregulated at the plasma membrane during infection with HIV." (PMID 33628210, 2021). "As also expected from previous studies, there was a high level of ECE1 and a relatively low one of SAP2 expression on day 3 post-infection." (PMID 31803172, 2019). "Infection of epithelial cells with the isogenic wild-type strain (BWP17+CIp30, here referred to as “WT”) or the ece1Δ/Δ+ECE1 parental control strain resulted in significant cellular damage compared to the vehicle (negative) control." (PMID 29362237, 2018). "Thirty-two genes are up-regulated in all infection models, and they include many genes related to hyphal formation (ALS3, ECE1, HWP1, SOD5, TEC1, UME6), zinc limitation (PRA1, ZRT1, ZRT2) and iron limitation (PGA7, RBT5)." (PMID 25693184, 2015). "Densitometry analysis confirmed that c-Fos was not expressed and MKP1 was not phosphorylated in response to infection with ece1Δ/Δ-containing mutant strains, but both were restored to WT-like levels in response to the ECE1 re-integrant strain." (PMID 41294335, 2026). "In summary, this study used CRISPR-Cas9 and homology-directed repair technology to construct homozygous gene knockouts of ALS3, ECE1, HGC1, and SAP2 in C. albicans, both individually and in combination, to investigate their combinatorial roles in the context of infection." (PMID 41294335, 2026). "Strikingly, deletion of NRG1 in 78048 reduced filamentation in vivo, expression of candidalysin (ECE1), and virulence without dramatically altering establishment of infection." (PMID 38376205, 2024). "HCMV IE86 reduced transcript levels of ET-1 early after infection, and HCMV also downregulated ECE-1 expression which resulted in an accumulation of the ET-1 precursor protein prepro-ET-1, and reduced levels of the mature ET-1 peptide in the supernatant of infected cells when IE86 was expressed." (PMID 34070407, 2021). "Of potential mechanistic importance, the ECE1/SAP2 expression ratio was in infected mice largely in favor of ECE1, whereas it was slightly above 1 in our VVC population, suggesting for a potentially different impact of SAP2 and candidalysin in human vs. mouse infection." (PMID 31803172, 2019). "The strain lacking ECE1 showed significantly higher transcript levels of ZRT2, PRA1, and ZRT3 after 24 h of infection of IECs, consistent with more severe zinc starvation." (PMID 38427950, 2024).
cancer (12 papers, 2008 to 2025). A tumor composed of atypical neoplastic, often pleomorphic cells that invade other tissues. "Considering that ECE1 is expressed as four variants and that isoform ECE1c has been shown to promote aggressiveness traits in other cancers, mRNA levels of these isoforms were analyzed by RT-qPCR." (PMID 40830989, 2025). "In blood of girls with high genistein concentrations in their urine, two proteins associated with cancer were down regulated: endothelin-converting enzyme (ECE-1) and eukaryotic translation initiation factor 3 subunit J (EIF-3)." (PMID 33330580, 2020). "Recombinant neprilysin and ECE1 inhibition led to decreased protein levels of vimentin and CD44, which are also associated to acquired stemness traits in several types of cancer." (PMID 40830989, 2025). "ECE1 is a metalloprotease responsible for activating big endothelin-1 (ET-1), a potent vasoconstrictor and mitogen and plays a role in cancer-related properties such as uncontrolled proliferation and invasiveness through the activation of ET-138." (PMID 38062093, 2023). "Previous studies unrelated to cancer have reported a relationship between HO-1 and the ECE-1/ET-1 pathway." (PMID 34199777, 2021). "ECE1 expression occurs in normal tissues and increased levels have been detected in samples of patients with different cancers." (PMID 32850305, 2020). "Endothelin-converting enzyme-1 (ECE1) activates the endothelin-1 peptide, which upregulates pathways that are related to diverse hallmarks of cancer." (PMID 32850305, 2020). "We provide evidence that the ECE-1 3′UTR is able to regulate the expression of ECE-1 and identify the presence of truncated transcripts generated from alternative polyadenylation in cancer cells." (PMID 24497914, 2014). "This is the first study to identify ECE-1 as a target for APA, a regulatory mechanism aberrantly activated in cancer cells, and provides novel information about the mechanisms leading to ECE-1 overexpression in malignant cells." (PMID 24497914, 2014). "The mechanisms regulating the expression of ECE-1 in cancer cells are poorly understood, hampering the development of novel therapies targeting the endothelin axis." (PMID 24497914, 2014). "Although ECE-1 has been reported in a number of cancers, specific isoforms present have yet to be identified." (PMID 18781169, 2008). "In carcinoma cells and ventricular myocytes, downregulation of ECE1 resulted in cell apoptosis." (PMID 37322475, 2023). "Indeed, a non ET-1-mediated effect of ECE1 on some malignant traits has been observed in several types of cancer cells as reviewed elsewhere." (PMID 32850305, 2020). "Endothelin-converting enzyme-1 (ECE-1) is the enzyme predominantly responsible for producing active endothelin-1 (ET-1), a mitogenic peptide implicated in the aetiology of a number of diseases, including cancer." (PMID 24497914, 2014). "In conclusion, the exploitation of the ECE-1 isoforms may lead to a new generation of molecular-targeted therapies for prostate and other cancers." (PMID 18781169, 2008). "The ECE-1 isoforms may, therefore, be relevant targets for antiinvasive therapy in prostate and other cancers." (PMID 18781169, 2008). "Work is ongoing to identify the precise molecular mechanisms underlying the 3′UTR-induced suppression of ECE-1 expression, but our findings suggest this may be a novel mechanism responsible for ECE-1 over-expression in cancer cells and may therefore represent a novel therapeutic target." (PMID 24497914, 2014). "ET1 has a plasma half-life of only 1 min, therefore, its pathophysiological effects depend on its continuous production by ECE1 and degradation by NEP, positioning these two proteins as potential targets to modulate the impact of ET1 in this cancer." (PMID 40830989, 2025). "Zinc metalloprotease endothelin-converting enzyme-1 (ECE-1), which has four isoforms, ECE-1a-d, has been found to be aberrantly expressed in several tumors and cancer cell lines." (PMID 36009534, 2022).